HES1 (hes family bHLH transcription factor 1)
Diseases named in the same sentence as HES1 in open-access papers (continued):
Sharing a sentence is not in itself a finding about the gene and the disease.
interstitial lung disease (1 paper, 2020). A diverse group of lung diseases that affect the lung parenchyma. "However, in the honeycomb cysts of IPF and scleroderma lungs, canonical Notch signaling target HES1 is upregulated, indicating that the persistent activity of Notch signaling may result in malfunction of LNEPs and account for abnormal alveolar repair in interstitial lung diseases." (PMID 33117807, 2020).
intestinal cancer (1 paper, 2017). "It is not fully known what genomic regions regulate Hes1 IEC expression and if these regions control aspects of Hes1’s transcriptional response to microbes or in intestinal cancer." (PMID 28850571, 2017).
kidney stone (1 paper, 2020). "Present study is the first report to demonstrate the relation between the HES1 protein and kidney stone formation and its associated kidney injury, however, further study of the mechanism involved is in need." (PMID 32867742, 2020).
large cell neuroendocrine carcinoma (1 paper, 2015). A usually aggressive carcinoma composed of large malignant cells which display neuroendocrine characteristics. "Hes1 directs cell division, in part, by repressing Pten expression in mouse, in human large cell neuroendocrine carcinoma, and in regenerating Clara cells of wild-type lungs." (PMID 26438299, 2015).
leprosy (1 paper, 2020). Leprosy is a chronic infectious disease affecting primarily the skin and peripheral nervous system. "The main histopathological finding of this research associated with the reduction in the expression of Hes-1 in the skin of leprosy patients is the inflammation found at the level of the dermis, skin annexes, and subcutaneous cellular tissue." (PMID 32265900, 2020). "The IHC evaluation allowed us to establish that the reduction in the expression of Hes-1 in the skin of leprosy patients is limited to three skin structures: epidermis, eccrine glands, and hair follicles." (PMID 32265900, 2020). "Differences in the expression of Hes-1 in eccrine glands and hair follicle between leprosy skin and non-leprosy skin." (PMID 32265900, 2020). "The reduced expression of Hes-1 in the epidermis of leprosy patients at the keratinocyte level would have a direct effect on the mechanisms of proliferation and differentiation in this cell." (PMID 32265900, 2020). "IHC of Hes-1 confirmed changes in expression in three skin structures of leprosy patients: epidermis, eccrine glands, and hair follicles." (PMID 32265900, 2020). "At the level of the skin annexes, we also showed differences in the expression of Hes-1 when comparing leprosy and non-leprosy samples." (PMID 32265900, 2020). "We found evident changes in the expression of two of the evaluated genes: Hes-1, downregulated 2.32 times, and Runx-1, upregulated 3.69 times in leprosy skin samples." (PMID 32265900, 2020). "Finally, the IHC findings of Hes-1 were validated through Western blot, showing a significant reduction in the expression of Hes-1 in the skin samples of leprosy patients (p < 0.05)." (PMID 32265900, 2020). "Therefore, the aim of this study was to establish the relationship between the expression of components of the Notch signaling pathway (Hes-1, Hey-1, Runx-1, Jagged-1, Notch-1, and Numb) with tissue changes in the skin and dermal nerve fibers of leprosy patients." (PMID 32265900, 2020). "Therefore, trophic changes in the epidermis of leprosy patients could be explained by M. leprae-induced neural damage and changes in Hes-1 expression." (PMID 32265900, 2020). "In the eccrine glands, we observed that in 80% of leprosy samples, the percentage of Hes-1-positive cells ranged from <1% to 25%, while in 93.4% of non-leprosy samples, the percentage of Hes-1-positive cells was greater than 75% (p < 0.0001)." (PMID 32265900, 2020). "On the other hand, the IHC analysis of Hes-1 allowed us to rule out that this transcription factor is being expressed in the dermal nerve fibers of leprosy patients." (PMID 32265900, 2020). "Hes-1 was found to have reduced expression in 83.3% of the leprosy samples and increased expression in 67% of non-leprosy samples." (PMID 32265900, 2020). "On the other hand, based on the inflammatory mechanism explaining the reduction of Hes-1, we ask the question: why was the transcriptional factor Runx-1 not altered in leprosy patients, considering that some Notch transcription factors are affected in inflammatory environments?" (PMID 32265900, 2020).
mesothelioma (1 paper, 2019). A usually malignant and aggressive neoplasm of the mesothelium which is often associated with exposure to asbestos. "It has been reported that activating the Notch1/Hes1 pathway could accelerate cell invasion, migration and proliferation through the PI3k/AKT/mTOR pathway in acute T lymphocyte leukaemia and mesothelioma." (PMID 31382985, 2019).
metastatic cancer (1 paper, 2010). A carcinoma which has spread from the original site of growth to another anatomic site. "Hes1 expression is downregulated in non-metastatic cancer cell LNCaP compared with that in metastatic cancer cell C4-2B and may act as a tumor suppressor for primary prostate tumorigenesis." (PMID 21106062, 2010).
mucinous tumors (1 paper, 2021). "Consistently, the protein abundance of Notch1 intracellular domain (NICD), the major activator of canonical Notch signaling pathway, as well as Notch effector HES1, were markedly increased in KLN mucinous tumors relative to non‐mucinous tumors, as evidenced by IHC staining and statistical analyses." (PMID 33439550, 2021). "In contrast to non‐mucinous tumors, the mucinous tumors from KLN mice displayed significant up‐regulation of Notch pathway components including Hes1, Hes5, Hey1 and Hey2, but not Wnt nor Hedgehog signaling." (PMID 33439550, 2021).
myeloproliferative disorder (1 paper, 2016). A clonal hematopoietic stem cell disorder, characterized by proliferation in the bone marrow of one or more of the myeloid (i.e., granulocytic, erythroid, megakaryocytic, and mast cell) lineages. "This analysis focused on genes (Srpk2, Hes1, Mtor, Pdp1, Meis1, Gfi1, Foxo3, Stra13, Hif1α, and Cebpε) involved in HSC proliferation; maintenance of quiescence, growth, and stem cell exhaustion; and development of myeloproliferative disorder in young and geriatric mice." (PMID 27366154, 2016).
neuropathic pain (1 paper, 2019). Chronic pain caused by damage to nerve fibers. "SNL downregulated spinal Hes1 expression and its suppression of the CDK9 and RNAPII recruitment and RNAPII phosphorylation on the mGluR5 promoter segments to mediate the development of neuropathic pain." (PMID 31454988, 2019).
oligodendroglioma (1 paper, 2018). A well-differentiated (WHO grade II), diffusely infiltrating neuroglial tumor, typically located in the cerebral hemispheres. "For example, reduced expression of Notch targets, namely HES1, HEY1, and especially HEY2, was seen in clinically progressed oligodendroglioma, while HES5 expression was most associated with shorter survival on multivariable analysis." (PMID 30417117, 2018).
opisthorchiasis (1 paper, 2022). Infection with flukes of the genus Opisthorchis. "For the first time, using histological methods and real-time PCR analysis, we demonstrated the activation of the Jagged1/Notch pathway in liver fibrogenesis, including the activation of the Hes1 and Hey1 target genes during experimental opisthorchiasis in Mesocricetus auratus." (PMID 36355906, 2022).
ovarian serous adenocarcinoma (1 paper, 2023). An adenocarcinoma that arises from the ovary and is characterized by the presence of malignant epithelial cells that, in well differentiated tumors, resemble the epithelium of the fallopian tube or, in poorly differentiated tumors, show anaplastic features and marked nuclear atypia. "One such gene, HES1 was a known human transcription factor which is also reported to be overexpressed in advanced ovarian serous adenocarcinoma, contributing to its stemness, metastasis, and drug resistance." (PMID 36899893, 2023).
pancreatic endocrine tumors (1 paper, 2010). "In breast and pancreatic endocrine tumors, Hes1 was also downregulated." (PMID 21106062, 2010).
pituitary adenomas (1 paper, 2017). "Furthermore, microarray analysis performed in the fractioned SP and main population from human GH and non functioning pituitary adenomas cells showed more than 1.5 fold increased expression of components of the Notch system in the SP, including HES1, JAG1 and NOTCH paralogs." (PMID 28915655, 2017). "In human pituitary adenomas we showed NOTCH1-4 receptors, JAGGED1 ligand and HES1 target gene expression with positive correlations between NOTCH1,2,4 and HES1, and NOTCH3 and JAGGED1 denoting Notch system activation in a subset of tumors." (PMID 28915655, 2017). "Both findings point to an activation of Notch signaling in some pituitary adenomas, in which the ligand JAGGED1 and the target HES1 would be paramount." (PMID 28915655, 2017).
posttraumatic stress disorder (1 paper, 2019). "Inactivation of Hes1 in excitatory neurons led to abnormal retention of fear memory, which is similar to the symptom of posttraumatic stress disorder (PTSD)." (PMID 31160641, 2019).
prolactinomas (1 paper, 2017). "A significant reduction in Hes1 mRNA levels was found in the anterior pituitaries of the lacDrd2KO mice bearing prolactinomas compared to Drd2loxP/loxP mice." (PMID 28915655, 2017). "Additionally, we show that Notch target gene Hes1 and Hey2 levels were decreased in prolactinoma cell lines, in line with a previous finding in human prolactinomas, while on the contrary, Hey1 was overexpressed in GH3 cells." (PMID 28915655, 2017). "There are also few data describing the Notch system in animal models of prolactinomas, even though several components of the Notch pathway such as NOTCH3, ASCL1 and HES1 are altered in human prolactinomas." (PMID 28915655, 2017). "Prolactinomas harbored by lacDrd2KO mice expressed high levels of NOTCH1 active domain and reduced Hes1." (PMID 28915655, 2017).
prostate adenocarcinoma (1 paper, 2014). "To know the relative contributions of PTOV1 and Notch signaling to malignancy in PC, we analyzed the expression of PTOV1, HEY1 and HES1 in 45 prostate adenocarcinomas and control associated benign peripheral zone (BPZ) by real-time RT-PCR." (PMID 24684754, 2014).
rectal tumor (1 paper, 2021). "HES1 expression levels in distal rectal tumors ranged from 0.59 to 42.67 with a median of 8.28, while in proximal rectal tumors it ranged from 0.6 to 62.05 with a median of 3.39." (PMID 34582650, 2021). "Results displayed that HES1 mRNA levels were significantly elevated in rectal tumor relative to normal tissues." (PMID 34582650, 2021). "Aiming to explore the clinical significance of Notch signaling in RC, the possible relation between HES1 and ATOH1 expression levels and various clinicopathological characteristics of rectal tumors were studied to evaluate their prognostic potential." (PMID 34582650, 2021). "Relative quantitative expression of LGR5, HES1 and ATOH1 in rectal tumor tissues compared to paired non-tumor adjacent tissues revealed significant overexpression of LGR5 and HES1 (p <0.001)." (PMID 34582650, 2021).
renal cell carcinoma (1 paper, 2023). "Although the aberrant activation of NOTCH1 pathway causes a malignant progression of renal cell carcinoma (RCC), the precise molecular mechanisms behind the potential action of pro-oncogenic NOTCH1/HES1 axis remain elusive." (PMID 36973704, 2023).
retinal degeneration (1 paper, 2022). Degeneration of the retina. "Taken together, our study demonstrated that miR-381-3p regulated RPCs proliferation and differentiation by targeting Hes1, which provides an experimental basis of RPCs transplantation therapy for retinal degeneration." (PMID 35281083, 2022).
schwannoma (1 paper, 2024). A benign, usually encapsulated slow growing tumor composed of Schwann cells. "At least partially, this may be causative for the reduced Sox10 protein levels measured in Hes1/Tle4-transfected S16 Schwannoma cells." (PMID 38791273, 2024). "We found strong repression of U1 enhancer activity by Hes1 and of the U3 activity by Tle4 or Hes1 in Sox10-positive S16 Schwannoma cells." (PMID 38791273, 2024). "To elucidate if Sox10 expression is indeed regulated by Tle4 and Hes1, we used S16 Schwannoma cells and quantified the signal intensity of endogenous Sox10 immunofluorescence in these cells by flow cytometry after transfecting them with control plasmids or plasmids encoding Hes1, Tle4, or both." (PMID 38791273, 2024).
systemic sclerosis (1 paper, 2015). A chronic disorder, possibly autoimmune, marked by excessive production of collagen which results in hardening and thickening of body tissues. "In systemic sclerosis (SSc), activation of Notch signaling resulted in an SSc-like phenotype with increased release of collagen and differentiation of resting fibroblasts into myofibroblasts, which required the presence of Jagged1 and Hes1." (PMID 26076648, 2015).
thymic tumors (1 paper, 2013). "Notch1 transcript, activated NICD and downstream effectors of NOTCH1 signaling, including MYC and HES1, are all expressed at high levels in R26PR-derived thymic tumors." (PMID 24046360, 2013).
thyroid (1 paper, 2011). "As TSH is secreted from E14.5 by the pituitary gland and TSH-receptor protein is expressed in the thyroid from E14.5 onwards, thyroid hypoplasia noted before E14.5 in Hes1−/− mice cannot be ascribed to TSH/TSH-receptor activity." (PMID 21364918, 2011).
thyroid tumor (1 paper, 2017). A benign or malignant neoplasm affecting the thyroid gland. "A significant downregulation of HES1 in thyroid tumors with high miR-182 level compared to patient samples from normal thyroid glands, was also verified by qRT-PCR." (PMID 28122586, 2017).
transposition of the great arteries (1 paper, 2021). A congenital cardiac defect in which two heart vessels are reversed (transposed). "Interestingly, the HES1 homozygous variant was strongly associated with transposition of the great arteries (TGA) (OR: 3.726, 95% CI: 1.637–3.207, p = 0.0003)." (PMID 33585489, 2021).
tuberculosis meningitis (1 paper, 2018). "Moreover, NICD1, Hes1, and MMP9 levels were increased in brain tissue samples from patients with tuberculosis meningitis." (PMID 29867921, 2018).
uterine cancer (1 paper, 2022). Primary or metastatic malignant neoplasm involving the uterine corpus and/or the cervix. "Expression alterations of NOTCH2, NOTCH3, NOTCH4, JAG2, and HES1 were evaluated as independent and significant prognostic factors for uterine cancer patients." (PMID 35136410, 2022). "NOTCH2, NOTCH3, NOTCH4, JAG2, and HES1 may be used as independent and significant prognostic factors for uterine cancer patients." (PMID 35136410, 2022).
vascular dementia (1 paper, 2021). A degenerative vascular disorder affecting the brain. "The H2S generating molecule sodium hydrosulfide (NaHS) has been shown to activate Notch pathway by increasing Jag1 and Hes1 in the hippocampus in a vascular dementia rat model." (PMID 34336718, 2021).
vitamin D deficiency (1 paper, 2022). A nutritional condition produced by a deficiency of VITAMIN D in the diet, insufficient production of vitamin D in the skin, inadequate absorption of vitamin D from the diet, or abnormal conversion of vitamin D to its bioactive metabolites. "In aging rats with vitamin D deficiency, there was a decrease in the protein expression of the Nocth1 transmembrane fragment and the mRNA expression of Hes1, the target gene of Notch signaling." (PMID 36364820, 2022).
Werner syndrome (1 paper, 2024). "By analyzing the molecular alterations in mouse model with accelerated aging phenotypes due to loss of p21 function in a Werner syndrome background, we observed that Wnt3 and β-Catenin were down-regulated, while Notch1 and Hes1 were up-regulated." (PMID 39341834, 2024).
tumor (263 papers, 2005 to 2026). "This review comprehensively introduces the mechanisms of Hes1 in the progression of malignant tumors, with a particular focus on discussing its application and underlying mechanisms in tumor immunotherapy." (PMID 40755759, 2025). "In particular HES1, hypomethylation-linked activation of which leads to tumor cell proliferation and inhibition of differentiation of these tumor cells into intestinal epithelial cells." (PMID 37860822, 2023). "As a primary target of Notch signaling pathway, HES1 has previously been shown to regulate tumor cell proliferation and survival, and silencing HES1 causes both growth arrest and apoptosis." (PMID 37071208, 2023). "A similar decrease in HES1 and mTOR expressions was also observed in tumours derived from ADAM17‐deficient MFE296 cells." (PMID 37165578, 2023). "Loss of HES1 also plays a role in rewiring the tumor immune microenvironment to induce immune suppression." (PMID 37749297, 2023). "Immunostaining of HCC tissues from Jag1-MxKO mice confirmed a complete loss of Jag1 expression, but Hes1 expression remained unchanged, especially in the peripheral regions of the tumor." (PMID 35064244, 2022). "Nevertheless, other studies indicated that the expression levels of HES1 were associated with the pathological tumor type and degree of differentiation." (PMID 34582650, 2021). "Linc-OIP5 induces proliferation and migration through NOTCH1 (Notch homolog 1, translocation-associated), YAP (yes-associated protein 1), JAG1 and HES1 (hairy and enhancer of split-1) and downregulating its expression reduced tumor growth in vivo." (PMID 34316694, 2021). "It induces proliferation and migration processes through Notch-1, yes-associated protein 1 (YAP), Jagged-1 (Jag-1) and hairy and enhancer of split-1 (Hes-1) and the down-regulation of its expression reduces tumor growth in vivo." (PMID 30583549, 2018). "On the other hand, mutations that downregulate expression of Hes-1 or Jagged-1 (one of the Notch ligands) in APCMinmice reduced the proliferation of tumor cells." (PMID 30323897, 2018). "Depletion of PEDF significantly decreased expression levels of Sox2, NICD, and Hes1 and caused GSCs to form tumor mass that was more restricted to the injection site." (PMID 25992628, 2015). "Previous studies showed that inhibition of Notch1 via suppression of γ-secretase activity reduces c-Myc and Hes1 levels, which was associated with decreased tumor cell proliferation." (PMID 25879451, 2015). "Our observations revealed that Hes1 overexpression causes the reduced expression of membranous and cytoplasmic β-catenin, and didn't lead to nuclear β-catenin accumulation in tumor section formed from Hes1-expressing CNE2 cells." (PMID 26452025, 2015). "As Notch1 expression is associated with tumor stage, we evaluated the expression of Hes1 in human CRC tissues." (PMID 26650241, 2015). "On the contrary, Hes1 expression was associated with the tumor size (T classification) (P = 0.018), lymph node invasion (N classification) (P = 0.006), metastasis (M classification) (P = 0.021), and clinical stage (P = 0.001) of 103 NPC patients." (PMID 26452025, 2015). "In total, 30 of 51 (58.8%) Notch/HES1 pathway associated genes examined were significantly different between tumor and normal bone (p < 0.05, q < 0.05); 23/30 (76.7%) had increased expression in tumors." (PMID 23816051, 2013). "The Notch pathway has been linked to the fraction of MB tumor cells that harbour precursor stem-cell markers, and HES1 has a role in self-renewing of multipotent progenitor cells." (PMID 19308264, 2009). "Notably, Hes1 modulates immunotherapy response: its conditional knockout in tumor-associated macrophages enhances cytotoxic T-cell infiltration/activation, suppressing tumor growth." (PMID 40755759, 2025).